KIF13B (kinesin family member 13B)
Description:
Involved in reorganization of the cortical cytoskeleton. Regulates axon formation by promoting the formation of extra axons. May be functionally important for the intracellular trafficking of MAGUKs and associated protein complexes.
Synonyms: GAKIN; KIAA0639
Tractability: Small molecule: a structure with a bound ligand is known. PROTAC: ubiquitination databases record sites on it; its protein half-life has been measured.
Gene: Protein-coding gene on chromosome 8 (29,067,278 to 29,263,124, reverse strand). Ensembl gene ENSG00000197892.
Subcellular location: Cytoplasm, cytoskeleton; Cell projection, axon
Pathways (Reactome):
Hemostasis: Kinesins
Vesicle-mediated transport: COPI-dependent Golgi-to-ER retrograde traffic
Gene Ontology:
Molecular function: 14-3-3 protein binding; protein binding; protein kinase binding; microtubule motor activity; ATP binding; microtubule binding
Biological process: regulation of axonogenesis; microtubule-based movement; protein targeting; signal transduction; T cell activation; establishment of protein localization
Cellular component: axon; cytoplasm; kinesin complex; cytoskeleton
Genetic constraint (gnomAD): Loss-of-function variants: 95 observed, 152.68 expected, observed/expected ratio (o/e) 0.62, 90% interval 0.53 to 0.74. The upper end of that interval is the gene's LOEUF score, 0.74, which puts it in group 3 of 6, group 1 being the genes least tolerant of losing a copy. Missense variants: 1,833 observed, 1,918.7 expected, observed/expected ratio (o/e) 0.96, 90% interval 0.92 to 0.99. Synonymous variants: 852 observed, 758.29 expected, observed/expected ratio (o/e) 1.12, 90% interval 1.06 to 1.19.
Homologues: Orthologues: chimpanzee KIF13B (99% identical), macaque KIF13B (98% identical), dog KIF13B (91% identical), rabbit KIF13B (90% identical), mouse Kif13b (89% identical), guinea pig KIF13B (88% identical), rat Kif13b (88% identical), tropical clawed frog kif13b (76% identical), zebrafish kif13ba (68% identical), zebrafish kif13bb (64% identical), pig KIF13B (54% identical). Paralogues in human: KIF13A (54% identical), KIF1A (27% identical), KIF1B (27% identical), KIF1C (20% identical), KIF16B (20% identical), KIF14 (19% identical), KIF21B (15% identical), CENPE (15% identical), KIF21A (15% identical), KIF4A (13% identical), KIF17 (13% identical), KIF4B (13% identical), and 29 more.
Diseases named in the same sentence as KIF13B in open-access papers:
KIF13B is named in the same sentence as 25 diseases in open-access papers, as found by Europe PMC text mining. Sharing a sentence is not in itself a finding about the gene and the disease. The quoted sentences say what the papers report.
atherosclerosis (2 papers, 2025 to 2026). A disease characterized by the build-up of fatty material and calcium deposition in the arterial wall resulting in partial or complete occlusion of the arterial lumen. "Furthermore, Kif13b deficiency accelerated atherosclerosis in the context of MAFLD." (PMID 40038775, 2025). "Given the known association between MAFLD and atherosclerotic cardiovascular disease (ASCVD), the present study investigated the potential causal link between Kif13b deficiency and atherosclerosis in the context of MAFLD." (PMID 40038775, 2025). "Furthermore, Kif13b deficiency accelerates atherosclerosis in the context of MAFLD." (PMID 40038775, 2025). "Altogether, these findings suggest that Kif13b may represent a potential therapeutic target for the treatment of atherosclerosis in the presence of MAFLD." (PMID 40038775, 2025). "Our results unveil a VSMC-specific atheroprotective role for KIF13B, define the KIF13B/KCTD10/KLF4 pathway as a key regulatory axis governing VSMC fate and plaque stability, and validate the therapeutic potential of KIF13B for treating advanced atherosclerosis." (PMID 41609725, 2026).
fatty liver disease (2 papers, 2025 to 2026). A reversible condition wherein large vacuoles of triglyceride fat accumulate in liver cells via the process of steatosis. "Rodents with global or liver-specific knockout of the Kif13b gene exhibit spontaneous hepatic steatosis, which is further exacerbated by different overnutrition diets." (PMID 40038775, 2025). "Rodents with global or liver-specific knockout of the Kif13b gene exhibited spontaneous hepatic steatosis, which was further exacerbated by different overnutrition diets." (PMID 40038775, 2025). "However, the implication of KIF13B in metabolic dysfunction-associated fatty liver disease (MAFLD) has not been explored yet." (PMID 40038775, 2025).
glioma (2 papers, 2023 to 2025). A benign or malignant brain and spinal cord tumor that arises from glial cells (astrocytes, oligodendrocytes, ependymal cells). "Consistently, with the increase in risk score, the expression of KIF4A and KIF13B, as well as the mortality rate of glioma patients, increased remarkably." (PMID 36837615, 2023).
melanoma (2 papers, 2022 to 2024). A malignant, usually aggressive tumor composed of atypical, neoplastic melanocytes. "Our functional esiRNA screen identified five candidate translation targets of VARS (that is, HADH, KIF13B, SLC7A5, QDPR and GOLT1B), whose depletion re-sensitizes resistant melanoma cells to MAPK therapy." (PMID 38849541, 2024). "We also determined the role of KIF13B in cancer growth and angiogenesis by stably transfecting B16F10 melanoma with firefly luciferase (luc2) and injecting these cells s.c. in the right flank of Kif13biECKO and Kif13bWT." (PMID 34670814, 2022).
acute monocytic leukemia (1 paper, 2025). Acute monoblastic leukemia (AML-M5), is one of the most common subtypes of acute myeloid leukemia (AML) that is either comprised of more than 80% of monoblasts (AML-M5a) or 30-80% monoblasts with (pro)monocytic differentiation (AML-M5b). "LPS treatment significantly reduced KIF13B mRNA and protein levels in differentiated human acute monocytic leukemia cells (THP1 macrophages)." (PMID 40963913, 2025).
aortic aneurysm (1 paper, 2025). A ruptured aneurysm located in the wall of the proximal portion of the descending aorta proceeding from the arch of the aorta. "First, our investigation revealed a significant reduction in KIF13B expression levels within aortic aneurysm lesions from both human patients and multiple mouse AAA models." (PMID 40963913, 2025). "Global inactivation of Kif13b or macrophage specific deletion of Kif13b exacerbated the development of aortic aneurysm in PPE or ANG II-infused mouse models." (PMID 40963913, 2025).
colon cancer (1 paper, 2023). "In addition, a target of miR-1290, KIF13B, is typically involved in the activation Wnt pathway and increases the expression of reprogramming-related transcript factors c-Myc and Nanog in colon cancer tissues." (PMID 36837615, 2023).
familial hypercholesterolemia (1 paper, 2025). An inheritable form of hyperlipidemia, in which there are excess lipids in the blood. "As expected, the inactivation of Kif13b promoted atherosclerotic development in both mice and hamsters with familial hypercholesterolemia, a condition where such lesions are prominently featured." (PMID 40038775, 2025).
fibrosis (1 paper, 2026). the formation of excess fibrous connective tissue in an organ or tissue in a reparative or reactive process. "Consistent with improved cardiac function, restoring PLIN5 in Kif13b−/− mice attenuated myocardial fibrosis and lipid accumulation and more profoundly, reduced oxidative stress relative to that in Kif13b−/− controls." (PMID 41531892, 2026).
lipid metabolism disorders (1 paper, 2025). "Collectively, these data indicated that Kif13b deficiency in hepatocytes is sufficient to cause lipid metabolism disorders and to exacerbate MASH and fibrosis in hamsters." (PMID 40038775, 2025).
liver fibrosis (1 paper, 2025). "Additionally, analysis of liver fibrosis using Sirius red staining revealed a significant increase in fibrosis in Kif13b−/− mice as well." (PMID 40038775, 2025).
metabolic dysfunction-associated steatohepatitis (1 paper, 2025). Metabolic dysfunction-associated steatohepatitis (MASH, formerly known as nonalcoholic steatohepatitis or NASH) is a type of fatty liver disease. "Overexpression of human KIF13B by lentivirus effectively prevented metabolic dysfunction-associated steatohepatitis (MASH) in methionine-choline-deficient diet (MCD)-fed mice." (PMID 40038775, 2025).
Sepsis (1 paper, 2026). Sepsis is defined as life-threatening organ dysfunction caused by a dysregulated host response to infection. "In the present study, we revealed that the KIF13B/PLIN5 axis serves as an important regulatory machinery in cardiac lipid homeostasis during sepsis." (PMID 41531892, 2026). "Kif13b−/− mice subjected to sepsis exhibited exacerbated cardiac dysfunction, increased mortality, heightened fibrosis, pronounced lipid accumulation, and enhanced oxidative stress." (PMID 41531892, 2026). "Given the vital dependence of cardiac function on precise lipid metabolic regulation and the established link between lipid dysregulation and SICD, we postulated that KIF13B might play a previously unrecognized role in protecting the heart during sepsis." (PMID 41531892, 2026).
steatosis (1 paper, 2025). Increased lipid within the cytoplasm of cells. "A significant increase in the content of TG was observed in the livers of Kif13b−/− mice, accompanied by more severe pathological steatosis, inflammation, and fibrosis when compared with control group." (PMID 40038775, 2025).
tumor (8 papers, 2015 to 2024). "ASAP2, DNM2 and KIF13B encoding signal transduction proteins play crucial roles in tumor proliferation and invasion." (PMID 38529307, 2024). "The effects of KIF13B expression in EC in tumor angiogenesis were examined by immunohistochemistry (IHC) of CD31 in tumor tissue." (PMID 34670814, 2022). "Interestingly, tumor angiogenesis and tumor growth were both inhibited by interfering with the interaction between KIF13B and VEGFR2 by the peptide kinesin-derived angiogenesis inhibitor (KAI)." (PMID 34670814, 2022). "Immunocytochemistry showed KIF13A and KIF26A mainly localized in cytoplasm and membrane, and KIF13B and KIF4A mainly concentrated at membrane and nuclear that significantly upregulated in tumor samples." (PMID 36837615, 2023). "Our results demonstrated that deletion of KIF13B in ECs severely impaired VEGF-A-induced neovascularization and tumor angiogenesis." (PMID 34670814, 2022). "Using an EC-specific KIF13B knockout (Kif13biECKO) mouse model, we demonstrated the function of EC expressed KIF13B in mediating VEGF-A-induced vascular leakage, angiogenesis, tumor growth, and cancer metastasis." (PMID 34670814, 2022). "This study demonstrated that inhibition of KIF13B-mediated VEGFR2 trafficking inhibited VEGF-A-induced pathological angiogenesis, vascular leakage, and thereby tumor metastasis." (PMID 34670814, 2022). "Finally, KIF4A, KIF13A, KIF13B, and KIF26A were identified from the HPA database, and all these KIFs differentially expressed between normal and tumor samples." (PMID 36837615, 2023). "In addition, we found seven other genes recurrently affected by HBV integration in tumour tissue samples: ECE1, EVI5L, KIF13B, MTX1P1, PLXND1, TECR and USP24." (PMID 37400627, 2023). "Interestingly, five genes (CDC45, KIF13B, ORC6, SHCBP1,and CAPN8) were not present in previously reported molecular tumor grading signatures." (PMID 26474389, 2015).
cancer (6 papers, 2021 to 2025). A tumor composed of atypical neoplastic, often pleomorphic cells that invade other tissues. "Competitive inhibition of interaction between VEGFR2 and KIF13B by a peptide kinesin-derived angiogenesis inhibitor (KAI) prevented pathological angiogenesis in models of cancer and eye disease associated with defective angiogenesis." (PMID 34670814, 2022). "KIF13B, the largest member of kinesin-3 family, possesses multiple functions, including cellular signaling transduction, receptor trafficking and cell division 15,32-34, and its deficits are associated with neurodegeneration, developmental defect and cancer 18,35,36." (PMID 40963913, 2025). "We demonstrated the fundamental role of KIF13B-mediated VEGFR2 trafficking in the mechanism of cancer metastasis." (PMID 34670814, 2022). "MiR-1290 promotes the reprogramming of cancer cells by targeting kinesin family member 13B (KIF13B), which is involved in cytokinesis, the final step in cell division, that leads to nuclear re-fusion in cells, and aneuploidy, which is present in malignant tumors, including CRC." (PMID 35163157, 2022). "And the inhibitory effect of KAI was observed only in the presence of KIF13B in EC, suggesting the main target of KAI is KIF13B-mediated VEGFR2 trafficking in EC, not survival of cancer cells in the bloodstream nor colonizing of cancer cells in the lungs." (PMID 34670814, 2022).
cardiovascular disease (2 papers, 2025 to 2026). "Considering the therapeutic potential of senolytics in cardiovascular diseases, we tested quercetin, a well-established senolytic agent 27, in Kif13b-/- BMDMs." (PMID 40963913, 2025). "Kinesin family member 13B (KIF13B) has been identified as a critical protective factor for metabolic disorder and cardiovascular disease; however, the role of KIF13B in SICD remains unknown." (PMID 41531892, 2026). "Given the established links between dyslipidemia, MAFLD, and cardiovascular disease (CVD) 22,23, we herein hypothesized that KIF13B might influence AAA pathogenesis." (PMID 40963913, 2025).
neurodevelopmental disorder (1 paper, 2024). A behavioral and cognitive disorder with onset during the developmental period that involves impaired or aberrant development of intellectual, motor, or social functions. "Also, we have identified 15 de novo variants in genes that were previously implicated in ASD or related neurodevelopmental disorders (PHF21A, WASF1, TCF20, DEAF1, MED13, CREBBP, KDM6B,SMURF1, ADNP, CACNA1G, MYT1L, KIF13B, GRIA2, CHM, and KCNK9)." (PMID 38572415, 2024).
KIF13B also shares sentences with these, for which no sentence is quoted: metabolic disease (2 papers); abdominal aortic aneurysm (1); ciliopathies (1); endometriosis (1); heart failure (1); Hepatic steatosis (1); hyperlipidemia (1).